ATM (ATM serine/threonine kinase)
Diseases named in the same sentence as ATM in open-access papers (continued):
Sharing a sentence is not in itself a finding about the gene and the disease.
ataxia telangiectasia (continued). "Evidence suggests that ATM-deficient mammalian cells or cells derived from patients with ataxia-telangiectasia syndrome (A-T) present with high ROS levels and hypersensitivity to agents that cause oxidative damage." (PMID 30265735, 2018). "Deficiency in the DNA repair kinase ATM leads to a fatal autosomal recessive neurological disease known as ataxia telangiectasia (AT)." (PMID 29670103, 2018). "ATM is mutated in the neurodegenerative disease Ataxia-Telangiectasia, thus providing another potential link between R-loops and neuronal health." (PMID 29419415, 2018). "Ataxia-telangiectasia (A-T) is a complex disease arising from mutations in the ATM gene (Ataxia-Telangiectasia Mutated), which plays crucial roles in repairing double-strand DNA breaks (DSBs)." (PMID 30515174, 2018). "Ataxia-telangiectasia (A-T) is a neurodegenerative disease caused by mutation of the A-T mutated (ATM) gene." (PMID 29338042, 2018). "Ataxia telangiectasia (AT) is a rare autosomal recessive disorder caused by mutation in the Ataxia telangiectasia mutated (ATM) gene." (PMID 30279714, 2018). "Ataxia telangiectasia (AT) is a primary immunodeficiency caused by mutations in the ATM gene and associated with an increased incidence of cancers, particularly EBV-associated lymphomas." (PMID 30662441, 2018). "ATM plays an essential role in redox balance, which contributes to the notable susceptibility of patients with ataxia-telangiectasia (AT) to bacterial infections." (PMID 29661984, 2018). "In humans, loss of function in ATM results in ataxia telangiectasia (A-T), a pleiotropic disease whose hallmarks include neurodegeneration, cancer-proneness, premature aging, radio-sensitivity, metabolic, and immune dysfunctions." (PMID 29616191, 2018). "The ataxia-telangiectasia mutated (ATM) protein kinase has been extensively studied for its role in the DNA damage response and its association with the disease ataxia telangiectasia." (PMID 29238697, 2017). "ATM (ataxia telangiectasia mutated) gene causes ataxia telangiectasia syndrome when biallelic pathogenic variants are inherited." (PMID 28670351, 2017). "One of the MBC patients had biallelic ATM pathogenic variants and was noted to have a clinical history of ataxia-telangiectasia on the requisition form." (PMID 28008555, 2017). "Ataxia-telangiectasia (A-T), or Louis-Bar syndrome, which is associated with mutations in the ATM (ataxia-telangiectasia mutated) gene, is a rare hereditary disorder with multiple manifestations [OMIM 208900]." (PMID 29163336, 2017). "Homozygous mutations in ATM cause ataxia-telangiectasia, a rare inherited autosomal recessive disorder which affects the immune and nervous system, and leads to increased sensitivity to radiation." (PMID 28591191, 2017). "The loss of function of ATM leads to the genetic disorder ataxia-telangiectasia (A-T), characterized by cerebellar degeneration, immunodeficiency, radiation sensitivity, chromosomal instability, and cancer pre-disposition." (PMID 28356161, 2017). "Ataxia Telangiectasia (AT) is a rare incurable genetic disease, caused by biallelic mutations in the Ataxia Telangiectasia-Mutated (ATM) gene." (PMID 28679388, 2017). "Mutations in ATM occur in ataxia telangiectasia, a recessive disorder associated with radiosensitivity, cancer predisposition, immunodeficiency, and neuropathology." (PMID 28754146, 2017). "In ataxia-telangiectasia, missense ATM mutations lead to a nearly functional protein molecularly similar to the ATM protein that competes with the wild type and creates premature genomic instability and earlier disease onset." (PMID 28772289, 2017). "Mutations in the ATM gene cause a rare autosomal multisystemic disease known as Ataxia-telangiectasia (AT)." (PMID 29152614, 2017). "Ataxia-telangiectasia is caused by the genetic deficiency of ATM, and results in childhood disability and early death." (PMID 27022623, 2016).
ataxia telangiectasia (continued). "Ataxia telangiectasia (A-T) is a multisystemic disease caused by mutations in the ATM (A-T mutated) gene." (PMID 27022623, 2016). "Ataxia-telangiectasia is a recessive genetic condition of childhood neurodegenerative disease caused by mutations in the ATM gene." (PMID 27538496, 2016). "Our RNA-Seq studies have recently revealed activation of an NMD switch exon (termed NSE) deep in ATM (ataxia-telangiectasia, mutated) intron 28 in cells depleted of each subunit of the auxiliary factor of U2 small nuclear RNP (U2AF)." (PMID 27658045, 2016). "Mutation of ATM causes ataxia telangiectasia, a congenital disorder of malformation in various tissues." (PMID 27014071, 2016). "ATM deficiency, caused by mutations in the ATM gene, underlies a childhood neurodegenerative disease known as ataxia telangiectasia (A-T)." (PMID 27538496, 2016). "Mutations in Ataxia Telangiectasia Mutated (ATM) that cause ataxia telangiectasia are associated with elevated glycaemia and low insulin sensitivity in participants without diabetes." (PMID 26606753, 2016). "People with ataxia telangiectasia and those with germline ATM mutations are predisposed to cancer, while somatic ATM mutations and perturbed ATM signalling promote tumourgenesis." (PMID 26606753, 2016). "Ataxia telangiectasia is a well‐studied human disease caused by ATM mutations and characterized not only by neurological symptoms and immune deficiency but also by cancer predisposition." (PMID 26455503, 2016). "Germ-line inactivating mutations in the ATM gene cause ataxia-telangiectasia, a recessive genetic disorder with a high incidence of cancer." (PMID 27764772, 2016). "ATM mutations in the germ line result in ataxia-telangiectasia (A-T), a rare genetic syndrome associated with hypersensitivity to double-strand DNA breaks and predisposition to lymphoid malignancies." (PMID 27658045, 2016). "These genes, shown to function in mitochondria, are involved in the ataxia-telangiectasia-mutated/ATM-Rad 3-related DNA repair pathway." (PMID 26309815, 2015). "ATM (mutated in ataxia-telangiectasia (A-T) and members of the Mre11/Rad50/Nbs1 (MRN complex) play key roles in this process." (PMID 26512707, 2015). "Patients with the recessive disease ataxia telangiectasia (AT) and ATM-deficient mice exhibit immunodeficiency, genomic instability, and an increased risk for lymphoid malignancies." (PMID 26220524, 2015). "The ATM (Ataxia-telangiectasia mutated) gene was identified in 1995 from a genetic disorder called ataxia-telangiectasia (A-T)." (PMID 26610585, 2015). "ATM mutation leads to the cancer-predisposing genetic disorder ataxia-telangiectasia(A-T) which belongs to genomic instability syndromes." (PMID 25541996, 2014). "Deficient ATM activation in GDFs represents a molecular mechanism that is analogous to Ataxia-telangiectasia patients who display genetic inactivation of ATM and are highly susceptible to radiation carcinogenesis." (PMID 28250390, 2014). "Ataxia-Telangiectasia (A-T) is a rare autosomal recessive genetic disorder caused by mutations in the ATM (A-T mutated) gene (OMIM# 607585)." (PMID 25077176, 2014). "Disease-related types include epidermal growth factor receptor (EGFR) for cancer, Ataxia telangiectasia mutated (ATM) for Ataxia telangiectasia and Androgen receptor (AR) for liver cancer conserved in both mammals and fish." (PMID 25520927, 2014). "Hypomorphic mutations in ATR and ATM genes have been identified among patients carrying Seckel syndrome and ataxia-telangiectasia (A-T), respectively." (PMID 24500207, 2014). "Ataxia telangiectasia (AT) is a neurodegenerative autosomal recessive inherited disease caused by a defect in the ataxia–telangiectasia mutated (ATM) gene." (PMID 24637877, 2014).
ataxia telangiectasia (continued). "Patients with ataxia telangiectasia (A-T), carrying mutations at both ataxia telangiectasia mutated (ATM) alleles (ATM−/−), present with progressive cerebellar ataxia, susceptibility to cancer, immunodeficiency, insulin resistance and hyperglycemia." (PMID 24276232, 2014). "Ataxia-telangiectasia (A-T) is a rare autosomal recessive hereditary neurodegenerative and progressive disease caused by mutations in the ataxia-telangiectasia-mutated (ATM) gene that produce the absence or inactivation of ATM protein kinase." (PMID 25374730, 2014). "We first infected wild type human fibroblasts (IMR90) and fibroblasts isolated from ataxia-telangiectasia syndrome patients which have a mutation in the ATM gene." (PMID 25340842, 2014). "Loss of ATM activity, either by genomic mutation (ATM-deficient fibroblasts from an ataxia telangiectasia patient) or by administration of a chemical inhibitor (AAI, an inhibitor of ATM and ATR), blocks IGF-1-sCLU expression in senescent cells." (PMID 24937130, 2014). "This general observation has been reported for many radiosensitive DNA-PKcs mutant cells as well as for lymphocyte and fibroblast cells from ataxia-telangiectasia patients who have mutations in ATM." (PMID 24714417, 2014). "Mutations in the ATM gene give rise to ataxia-telangiectasia (A-T), which is characterised by immunodeficiency, cancer predisposition, neurodegeneration and also infertility." (PMID 24637776, 2014). "The best characterised of these is ataxia-telangiectasia (A-T) which arises due to mutations in the ATM gene." (PMID 24637776, 2014). "Inherited biallelic mutations of the ATM gene are responsible for thedevelopment of ataxia telangiectasia (AT)." (PMID 25614872, 2014). "ATM deficiency causes ataxia telangiectasia (AT), a genetic disorder that is characterized by premature aging, cerebellar neuropathy, immunodeficiency, and predisposition to cancer." (PMID 25247188, 2014). "Ataxia-telangiectasia mutated (ATM) is a serine threonine kinase originally identified as the product of the gene mutated in ataxia telangiectasia (AT)." (PMID 24681585, 2014). "Heritable mutations in ATM result in ataxia telangiectasia (AT), a rare recessive syndrome that is associated with progressive neurodegeneration, variable kinds of immune-deficiencies and a predisposition to lymphoid cancer." (PMID 23443494, 2013). "It becomes activated by the phosphatidylinositol 3-kinase-like serine/threonine kinases ATR (ataxia telangiectasia response) and ATM (ataxia telangiectasia mutated) through phosphorylation of Ser-317 and Ser-345 followed by autophosphorylation of Ser-296." (PMID 23483975, 2013). "The most evident example being the inherited autosomal recessive disorder, Ataxia-telangiectasia (A–T), which results from loss of ATM protein expression or functional protein product." (PMID 23437304, 2013). "Deficiencies in the ATM gene are the underlying cause for ataxia telangiectasia, a syndrome characterized by neurological, motor and immunological defects, and a predisposition to cancer." (PMID 23741392, 2013). "In Ataxia-Telangiectasia patients, 70%–90% of ATM mutations are nonsense, frame shift, or splicing mutations that truncate the protein." (PMID 24324828, 2013). "Among these genes, NPAT and ATM genes are associated with ataxia telangiectasia, one of the most frequent autosomal recessive cerebellar ataxias." (PMID 23977206, 2013). "Heterozygous carriers of Ataxia telangiectasia (AT)-causing mutations in the ATM gene have been associated with hereditary breast and ovarian cancer." (PMID 23344037, 2013). "Our results demonstrated that miR-26b promotes porcine granulosa cell apoptosis by targeting a member protein of the phosphatidylinositol-3-kinase-like enzyme family, ATM, which is mutated in the human disease ataxia telangiectasia." (PMID 22737216, 2012).
ataxia telangiectasia (continued). "Ataxia-telangiectasia, Nijmegen breakage syndrome and ataxia-telangiectasia-like disorder are defective in the ataxia-telangiectasia mutated (ATM), NBS1 and Mre11 genes, respectively." (PMID 24704845, 2012). "ATM gene has been described to be causal gene of Ataxia-telangiectasia, and inactivation of ATM is associated with increased risk of carcinogenesis and radiosensitivity." (PMID 22485171, 2012). "These are features of the ataxia-telangiectasia syndrome, seen in patients with loss of function of ataxia telangiectasia mutated protein (ATM)." (PMID 23185347, 2012). "Among the principal human genetic syndromes associated with DDR genes/proteins mutations, there is Ataxia Telangiectasia (AT), which is caused by an ATM mutation and is characterized by the development of cancers and neurodegenerative diseases." (PMID 21926946, 2011). "ATM was named for the autosomal recessive progressive neurodegenerative disease, ataxia-telangiectasia (AT), which is caused by mutations of ATM gene." (PMID 21980462, 2011). "Mutations in the ATM gene lead to the genetic disorder ataxia-telangiectasia (AT), which is characterized by cerebellar degeneration, immunodeficiency and an increased risk of cancer." (PMID 21037856, 2010). "The human condition ataxia-telangiectasia, which results from mutations in ATM, is associated with substantial neurodegeneration." (PMID 21191148, 2010). "To provide a genetic proof that ATM is required for syncytial apoptosis induced by HIV, we took advantage of HSV-transformed T lymphoblasts from patients with ataxia telangiectasia (A-T), which results from a loss-of-function mutation of ATM." (PMID 18560558, 2008). "Ataxia Telangiectasia (AT) is an autosomal recessive human disorder caused by mutational inactivation of the AT mutated (ATM) gene." (PMID 21892312, 2008). "ATM, the gene that is mutated in the hereditary disease ataxia-telangiectasia, codes for a protein kinase that acts as a master regulator of cellular responses to DNA double-strand breaks." (PMID 17940507, 2007). "From the genetic perspective, ATM is the gene mutated in ataxia-telangiectasia (AT), an autosomal recessive disorder phenotypically characterised by chromosomal instability and an increased risk for lymphoproliferative tumors in homozygotes." (PMID 16622469, 2006). "While mutations of both alleles of the ATM (Ataxia Telangiectasia Mutated) gene cause the rare autosomal recessive disorder ataxia telangiectasia (AT), heterozygous carriers of an ATM allele are healthy." (PMID 15942625, 2005). "Indeed, Ataxia–Telangiectasia (MIM#208900) is a rare inherited neurological disorder caused by bi-allelic loss-of-function (LOF) variants in ATM." (PMID 41596415, 2026). "An early childhood onset neurodegenerative disorder, ataxia telangiectasia (AT), affects one in 40,000 to 100,000 individuals worldwide and is caused by mutations in the ataxia telangiectasia mutated (ATM) threonine-serine kinase, which regulates the DNA damage response (DDR)." (PMID 41544707, 2026). "Interestingly, one CVID group exhibited signatures that are shared with ataxia-telangiectasia, which is caused by mutations in the ATM gene." (PMID 41419734, 2025). "Furthermore, Cremona and Behrens confirmed the link between ATM mutations and oncogenesis, explaining the high incidence of neoplastic diseases in patients with ataxia-telangiectasia." (PMID 41451872, 2025). "Similarly, ataxia-telangiectasia, caused by mutations in the ATM gene, is characterized by progressive cerebellar ataxia, telangiectasia, immunodeficiency, and cancer susceptibility." (PMID 41300699, 2025).
ataxia telangiectasia (continued). "Indeed, germline carriers of homozygous ATM mutations cause ataxia-telangiectasia, a human genetic disorder associated with the highest radiosensitivity." (PMID 40570257, 2025). "Ataxia-telangiectasia (A-T) is a rare neurodegenerative disorder caused by the deficiency of the serine/threonine kinase ataxia telangiectasia mutated (ATM) protein, whose loss of function leads to altered cell cycle, apoptosis, oxidative stress balance and DNA repair after damage." (PMID 40234386, 2025). "ATM (Ataxia Telangiectasia Mutated) protein is a serine/threonine protein kinase, and its deficiency is closely related to the human neurodegenerative disease Ataxia-Telangiectasia (AT)." (PMID 40860911, 2025). "ATM loss makes neurons more susceptible to degeneration, as seen in ataxia-telangiectasia." (PMID 41153431, 2025). "The most common example is ataxia telangiectasia (AT) caused by ATM gene mutation." (PMID 40542608, 2025). "These molecular pathways may function in diseases associated with ATM, including ataxia telangiectasia." (PMID 39226322, 2024). "According to research conducted on Ataxia Telangiectasia (A-T), a human radiation sensitivity disorder in which both ATM alleles are disabled, the most persuasive evidence indicating the function of ATM in maintaining redox equilibrium is gained from this condition." (PMID 38671922, 2024). "Ataxia-telangiectasia (A-T) is an autosomal recessive primary immunodeficiency disorder (PID) caused by biallelic mutations occurring in the serine/threonine protein kinase (ATM) gene." (PMID 38882696, 2024). "Here we showed loss of ATM in ataxia telangiectasia cells occurs with a reduced CD13 expression." (PMID 38933336, 2024). "Additionally, a heterozygous variant in the ATM gene (NM_000051.4: c.7891G>A; p.A2631T) in which homozygous or compound heterozygous variants are associated with ataxia‐telangiectasia (OMIM #208900) was identified." (PMID 39180521, 2024). "Ataxia telangiectasia (A-T), caused by biallelic variants in the ATM gene, is a multisystemic and severe syndrome characterized by progressive ataxia, telangiectasia, hyperkinesia, immunodeficiency, increased risk of malignancy, and typically death before the age of 30." (PMID 38404774, 2024). "The loss of ataxia–telangiectasia-mutated (ATM) protein causes a pleiotropic disease called ataxia–telangiectasia (AT), and its patients also develop neurodegeneration, specifically cerebellar Purkinje neurodegeneration, along with cancer and other immune dysfunctions." (PMID 38339107, 2024). "One of the most well-known examples is ataxia-telangiectasia (AT), which is a condition caused by homozygous or complete loss of function mutations in the ATM (ataxia telangiectasia, mutated) gene leading to impaired response to DNA (deoxyribonucleic acid) double-strand breaks." (PMID 38001574, 2023). "Ataxia telangiectasia is a monogenetic disorder caused by mutations in the ATM gene." (PMID 37938627, 2023). "Ataxia-telangiectasia, another type of ataxia with an autosomal recessive pattern of inheritance, is produced by localized mutations in the ATM gene (11q22.3) and is characterized by a cerebellar syndrome associated with a combined immunodeficiency that mainly affects the humoral immune response." (PMID 37754054, 2023). "Surprisingly, while the cause of aplastic anemia was not identified, the sibling Pat-1055 was found to be homozygous for a pathogenic variant in ATM thus establishing a clinically unsuspected diagnosis of ataxia telangiectasia syndrome and ruling out the possibility of serving as a donor." (PMID 37344829, 2023). "With regard to self-DNA detection, the murine ortholog of IFI16, IFI204, was found to mediate the detection of DNA released into the cytoplasm following DNA damage resulting from ataxia-telangiectasia mutated (ATM) deficiency in a murine model of ataxia telangiectasia (A-T)." (PMID 36999037, 2023).